FLG2 (filaggrin 2)
Description:
Essential for normal cell-cell adhesion in the cornified cell layers. Important for proper integrity and mechanical strength of the stratum corneum of the epidermis.
Synonyms: IFPS; PSS6
Tractability: Antibody: its Gene Ontology location is reachable by antibodies, with high confidence.
Target class: Adhesion
Gene: Protein-coding gene on chromosome 1 (152,348,735 to 152,360,006, reverse strand). Ensembl gene ENSG00000143520.
Subcellular location: Cytoplasm; Cytoplasmic granule
Pathways (Reactome):
Immune System: Neutrophil degranulation
Gene Ontology:
Molecular function: calcium ion binding; structural molecule activity; transition metal ion binding
Biological process: cell adhesion; epidermis morphogenesis; establishment of skin barrier
Cellular component: cytoplasm; nucleus; cornified envelope; extracellular region; keratohyalin granule; tertiary granule lumen
Genetic constraint (gnomAD): Loss-of-function variants: 7 observed, 4.6 expected, observed/expected ratio (o/e) 1.52, 90% interval 0.8 to 1.93. That is too few expected variants to judge how well the gene tolerates losing a copy. Missense variants: 2,700 observed, 2,860.9 expected, observed/expected ratio (o/e) 0.94, 90% interval 0.91 to 0.97. Synonymous variants: 1,031 observed, 1,065.4 expected, observed/expected ratio (o/e) 0.97, 90% interval 0.92 to 1.02.
Homologues: Orthologues: chimpanzee FLG2 (99% identical), macaque FLG2 (76% identical), mouse Flg2 (42% identical). Paralogues in human: HRNR (38% identical), FLG (28% identical), RPTN (10% identical).
Diseases named in the same sentence as FLG2 in open-access papers:
FLG2 is named in the same sentence as 47 diseases in open-access papers, as found by Europe PMC text mining. Sharing a sentence is not in itself a finding about the gene and the disease. The quoted sentences say what the papers report.
atopic dermatitis (10 papers, 2009 to 2025). "Filaggrin gene (FLG/FLG2) product deregulations are associated with various allergic skin diseases, including but not limited to atopic dermatitis, alopecia areata, and ichthyosis vulgaris." (PMID 40765578, 2025). "Filaggrin gene (FLG/FLG2) mutations and expression are associated with various allergic skin diseases, such as atopic dermatitis, alopecia areata, and ichthyosis vulgaris." (PMID 40765578, 2025). "FLG2 is known for its association with skin diseases including atopic dermatitis, as well as for its link to neurodevelopmental aberrations, leading to autism spectrum disorder (ASD) with a prenatal excessive cortical expansion frequently seen in ASD children." (PMID 39717325, 2024). "We also observed a highly significant association between the FLG2 SNP with disease severity; a patient carrying at least one FLG2 rs12568784 allele [T] was approximately four times more likely of having moderate atopic dermatitis." (PMID 36013110, 2022). "The presence of both risk factors, at least one HRNR rs877776[C] allele and at least one FLG2 rs12568784 [T] allele, strongly enhanced the risk of atopic eczema." (PMID 36013110, 2022). "The aim of this study was to investigate the association of SNPs in hornerin (HRNR) and filaggrin-2 (FLG2) genes with childhood atopic eczema, as well as other atopic phenotypes." (PMID 36013110, 2022). "Our results are in agreement with findings in a cohort of African-American children demonstrating that the rs12568784 variant in FLG2 was correlated with more persistent atopic eczema." (PMID 36013110, 2022). "Beyond indicating the association of HRNR rs877776 [C] and FLG2 rs12568784[T] with atopic eczema, our study demonstrated that these SNPs are also associated with allergic sensitization and susceptibility to the complex phenotype—asthma plus eczema." (PMID 36013110, 2022). "We demonstrated that risk variants of HRNR rs877776[C] and FLG2 rs12568784[T] were associated with atopic eczema, allergic sensitization, and susceptibility to the complex phenotype—asthma plus eczema." (PMID 36013110, 2022). "Analysis of the FLG2 rs12568784 polymorphism revealed a significant association with susceptibility to atopic eczema (for allele OR = 1.91; 95%CI 1.01–3.65; p = 0.003)." (PMID 36013110, 2022). "In the present study, we provided evidence for the highly significant association of the rs12568784 [T] allele in FLG2 with atopic eczema, and the severity of the disease." (PMID 36013110, 2022). "There is an association between polymorphisms in the filaggrin 2 gene (rs 12568784 and rs 1689937411) and persistent AD in African American patients with atopic dermatitis." (PMID 32151410, 2020). "Polymorphisms of the filaggrin 2 gene (rs 12568784 and rs 16899374) are associated with persistent atopic dermatitis in African American patients." (PMID 32151410, 2020). "Although it needs to be confirmed, the decreased expression of FLG2 in atopic eczema patients might be explained by genetic variants in the FLG2 gene." (PMID 36013110, 2022). "Based on these findings, it seems reasonable to assume that genetic variants in HRNR and FLG-2 genes might contribute to the pathogenesis of atopic eczema by possible influence on the gene expression or protein function." (PMID 36013110, 2022). "In conclusion, the present study indicates that risk variants in HRNR and FLG2 genes may contribute to atopic eczema susceptibility; for HRNR SNP, this effect seems to be independent of the well-established FLG risk alleles." (PMID 36013110, 2022). "Interestingly, functional studies have clearly demonstrated that decreased FLG2 expression is associated with disturbances in the process of keratinocyte differentiation and CE formation, suggesting the potential role of FLG2 downregulation in the epidermis impairment observed in atopic eczema." (PMID 36013110, 2022).
atopic dermatitis (continued). "Patients carrying at least one allele T for FLG2 SNP were two times more likely to have atopic eczema when compared to patients who did not carry any of these variants." (PMID 36013110, 2022). "Finally, the significant association between both risk factors with atopic eczema and eczema-associated asthma prompted us to determine the interactive effects of HRNR and FLG2 SNPs." (PMID 36013110, 2022). "The aim of our current study was to assess the association between the susceptibility to childhood atopic eczema as well as eczema-associated asthma and genetic variants in the HRNR and FLG2 genes, two worthy investigation members of the S-100-fused type protein family, which also includes FLG." (PMID 36013110, 2022). "Furthermore, the expression levels of HRNR and FLG-2 were shown to be significantly reduced in the skin of patients with atopic eczema, as was also demonstrated for FLG." (PMID 36013110, 2022). "In addition, our results reveal that HRNR and FLG2 variants and FLG loss-of-function mutations are candidate genes that might control the risk of atopic eczema in an interactive manner." (PMID 36013110, 2022). "Interestingly, the HRNR variant alone caused a significantly increased risk for atopic eczema, whereas the FLG2 [T] variant provided no additional disease risk in the absence of the HRNR [C] allele." (PMID 36013110, 2022). "In the current study, we assessed the importance of SNPs in HRNR and FLG2 genes in the susceptibility to childhood atopic eczema and whether this possible association is independent of the FLG risk alleles described previously in this population." (PMID 36013110, 2022). "Moreover, we investigated whether an interaction between HRNR and FLG2 SNPs and the four most common FLG mutations affected the atopic eczema risk." (PMID 36013110, 2022). "The human filaggrin-2 (FLG2) protein is another member of the SFTP family that shares common structural features with FLG and is believed to be involved in atopic eczema pathogenesis." (PMID 36013110, 2022). "Indeed, the expression level of FLG2 was found to be markedly reduced in lesional and nonlesional atopic eczema skin in comparison to healthy skin." (PMID 36013110, 2022). "Recent studies have shown that in addition to filaggrin abnormalities, abnormalities in the filaggrin-like proteins, hornerin and Filaggrin family member 2 (FLG2), are also involved in either the lesional or non-lesional skin barrier symptoms of atopic dermatitis." (PMID 32326002, 2020).
psoriasis (8 papers, 2009 to 2024). An autoimmune condition characterized by red, well-delineated plaques with silvery scales that are usually on the extensor surfaces and scalp. "In contrast, 3D skin equivalents made of GATA3 silenced keratinocytes which were cultivated under psoriasis like conditions showed increased FLG2 protein levels when compared to the correlated controls (controls shRNA) by trend." (PMID 28928464, 2017). "Within the keratinocyte differentiation signature subgroup that is down‐regulated in psoriasis, several genes, such as LCE1B, LCE2B, FLG2, and LOR, are known to be associated with the terminally differentiated keratinocytes (cornecytes) that make up the stratum corneum." (PMID 28008606, 2017). "Loricrin (LOR) was the most significantly downregulated gene in the psoriasis lesions, and filaggrin (FLG, FLG2) was also strongly downregulated." (PMID 36841845, 2023). "Together with the elevated CEBPB gene expression, the expression of keratinocyte terminal differentiation genes, such as IVL, FLG2, and TGM1, is upregulated in the lesional skin of psoriasis." (PMID 32751111, 2020). "The gene expression of FLG, FLG2, LOR, IVL, and S100A7 is differentially affected in atopic dermatitis (AD) and psoriasis." (PMID 32751111, 2020). "In a complex manner, these cytokines may be involved in the expression of FLG2 and HRNR and the pathogenesis of psoriasis." (PMID 39624730, 2024). "This study demonstrated that FLG2 and HRNR may play different roles in barrier formation and the pathogenesis of psoriasis." (PMID 39624730, 2024). "The dysregulated expression of FLG, FLG2, LOR, and IVL is known to be normalized by specific biologic treatments, for example, blockade of interleukin-4 (IL-4) and IL-13 in AD or blockade of IL-17A in psoriasis." (PMID 32751111, 2020). "Consequently, FLG2 and HRNR may play different roles in barrier formation and the pathogenesis of psoriasis." (PMID 39624730, 2024). "Furthermore, FLG2 and HRNR may play different roles in barrier formation and the pathogenesis of psoriasis." (PMID 39624730, 2024). "In the investigation of FLG2 immunoreactivity in skin biopsies from patients with AD and psoriasis vulgaris, two of the most common inflammatory skin diseases, we have observed decreased expression of FLG2 only in the lesional but not in uninvolved skin of psoriasis patients." (PMID 19384417, 2009). "No tendency for divergent gene expression of FLG, FLG2, IVL, LOR or HRNR in GATA3 silenced cells when compared to control cells was visible under psoriasis-like conditions." (PMID 28928464, 2017).
breast carcinoma (3 papers, 2021 to 2023). "FLG2, FMN2, and ERBB3 have been reported to be related to breast cancer." (PMID 35111673, 2021).
eczema (3 papers, 2019 to 2023). "In the present study, HRNR and FLG2 risk variants predicted the future development of eczema-associated asthma with a positive predictive value of approximately 50%, which improved considerably when these variants were combined with FLG mutations." (PMID 36013110, 2022). "However, we revealed that the risk alleles HRNR rs877776[C] and FLG2 rs12568784[T], predisposed to eczema-associated asthma, significantly increased the risk of this combined phenotype by nearly four times and more than five-fold, respectively." (PMID 36013110, 2022). "Thus, it seemed of interest to study the application of HRNR and FLG2 variants for eczema-associated asthma prediction." (PMID 36013110, 2022). "Finally, we investigated whether HRNR rs877776 and FLG2 rs12568784 risk variants can be used as predictive biomarkers for the development of eczema-associated asthma in young children." (PMID 36013110, 2022). "Both risk alleles, HRNR rs877776[C] and FLG2 rs12568784[T], conferred increased risks for asthma in this subgroup, indicating that these SNPs might provide genuine risks for the particular asthma phenotype occurring in the context of eczema." (PMID 36013110, 2022). "Here, the eczema-associated gene SPRR3 shows prominent fold regulation, indicating barrier function-related alterations alongside FLG2, AQP9 and several keratins in vivo." (PMID 37298605, 2023). "Next, we restricted the analysis to children with eczema and demonstrated a significant association between HRNR and FLG2 SNPs and allergic sensitization in this subgroup." (PMID 36013110, 2022). "Nevertheless, the analysis limited to children with eczema confirmed that the observed association between HRNR and FLG2 with eczema-associated asthma is not only due to the presence of coexisting eczema." (PMID 36013110, 2022). "In the case of eczema-associated asthma, both HRNR and FLG2 variants alone yielded significantly increased risks; however, the strongest effect was seen in the subjects who combined both at least one HRNR rs877776[C] allele and at least one FLG2 rs12568784 [T]." (PMID 36013110, 2022). "Our results could support this hypothesis as we demonstrated that HRNR and FLG2 risk variants were associated with allergic sensitization even in children without any allergic symptoms, including eczema." (PMID 36013110, 2022). "Interestingly, the combination of any tested risk variants, HRNR rs877776[C] or FLG2 rs12568784[T] with FLG mutations, provided the best combination of diagnostic specificity (100%) and predicted eczema plus the asthma phenotype with a positive predictive value of 100%." (PMID 36013110, 2022). "Interestingly, the effects of HRNR rs877776 and FLG2 rs12568784 risk alleles on allergic sensitization were also independent of concomitant allergic diseases, as the associations were significant in the subgroup of controls without eczema and asthma (OR = 9.04; 95%CI 2.28 ÷ −35.76; p = 0.002)." (PMID 36013110, 2022).
allergic disease (2 papers, 2020 to 2022). An immune response that occurs following re-exposure to an innocuous antigen, and that requires the presence of existing antibodies against that antigen. "In the present study, both risk alleles HRNR rs877776[C] and FLG2 rs12568784[T] provided significantly increased risks for allergic sensitizations and the effects were independent of concomitant allergic diseases." (PMID 36013110, 2022).
asthma (2 papers, 2022 to 2025). "Interestingly, we confirmed significant associations between both HRNR and FLG2 risk alleles and asthma in this subgroup." (PMID 36013110, 2022). "Additionally, VDR expression was lower in patients with comorbid asthma (p = 0.036), and significantly reduced levels of OCLN (p = 0.006), CTNNB1 (p = 0.004), and FLG2 (p = 0.046) were observed in patients with total serum IgE ≥ 100 IU/mL." (PMID 40649943, 2025).
ichthyosis (2 papers, 2020 to 2024). Disorders of cornification that are characterized by visible scaling and/or hyperkeratosis of most or all of the skin. "Nonsense homozygous mutations in FLG2 could induce ichthyosis and generalized peeling skin in humans." (PMID 39092175, 2024). "Meanwhile, we have discovered that the ichthyosis-related gene FLG2 was lost in the African manatee, which has also been observed in the dugong." (PMID 39092175, 2024). "The protein levels of FLG2 are also decreased in the SC and epidermis of AD patients, in the SC from dandruff condition, in a lipid raft disruption model and in ichthyosis peeling skin suggesting that FLG2 plays an important role in epidermal homeostasis and barrier formation." (PMID 32437351, 2020).
gastric adenocarcinoma (1 paper, 2020). "Present study results also correspond with the previously reported role of FLG2 mutations in early stages of carcinogenesis as they have been found in precancerous lesions but not in gastric adenocarcinoma or peritoneal gastric cancer metastases." (PMID 33255265, 2020).
glioblastoma multiforme (1 paper, 2017). "More recently, Yan and colleagues reported that FLG2 contributed to the progression of glioblastoma multiforme (GBM) through inducing multiple immunosuppression mechanisms." (PMID 27732962, 2017).
melanoma (1 paper, 2025). A malignant, usually aggressive tumor composed of atypical, neoplastic melanocytes. "High filaggrin mRNA expression (FLG and/or FLG2 transcripts) is associated with a poor overall survival in melanoma, and a positive correlation was observed in the expression patterns between the FLG and FLG2 transcripts." (PMID 40765578, 2025). "Therefore, based on the average of the combined FLG and FLG2 mRNA expressions, we classified the melanoma patients into the filaggrinHigh and filaggrinLow groups, respectively." (PMID 40765578, 2025).
ovarian carcinoma (1 paper, 2022). A malignant neoplasm originating from the surface ovarian epithelium. "For the first time, we report the immune‐related mutations of ZNF462, ADGRV1 and FLG2 in ovarian cancer." (PMID 35735060, 2022).
Pseudomonas infection (1 paper, 2015). Infections with bacteria of the genus pseudomonas. "The apparent absence of FLG2 at certain body surfaces, as in the lung or of burned skin, would explain their higher susceptibility towards Pseudomonas infections and make FLG2 C-terminal fragments and their derivatives candidates for new Pseudomonas-targeting antimicrobials." (PMID 26371476, 2015). "The present study indicates that C-terminal FLG2 fragments might be promising alternatives to traditional antibiotics used to cure especially Pseudomonas infections." (PMID 26371476, 2015).
pterygium (1 paper, 2021). A wedge-shaped fibrovascular lesion arising from the bulbar conjunctiva and extending to the cornea. "In our study, we found only minimal changes, with modest upregulation of KRT10 in pterygium and no expression of KRT1 in either pterygium or pinguecula; in addition, FLG2 was modestly upregulated in pinguecula." (PMID 34769520, 2021).
skin cancer (1 paper, 2020). "In addition to the mutations in genes known to be associated with skin cancer development, we identified multiple new UV target genes that harbor high frequency of T > C conversions, including GVINP1, NCF1B, FLG2, and SPEF2." (PMID 32188867, 2020).
tumor (7 papers, 2020 to 2026). "Collectively, the evidence suggests that HRNR, CRCT1, KPRP, and FLG2 promote cornification, which might underlie their potential tumor-suppressive action in relation to BC (see Discussion for details)." (PMID 37370814, 2023). "FLG2 was recently listed among “untouchable genes” with a deficit of loss-of-function mutations, suggesting that these genes may provide tumor cells with a survival advantage and eventually serve as alternative therapeutic targets." (PMID 33255265, 2020). "Other targets included Filaggrin-2, peroxiredoxin 6, Calmodulin-like protein 5, TBCEL-TECTA readthrough protein, Desmocollin 1 and 3, and Desmoplakin variant protein—with implications in diagnosis and tumour progression." (PMID 40725142, 2025). "Given that these BCs harbor 1q21.3 amplification and the increased copy numbers of HRNR, FLG2, CRCT1 and KPRP genes, these recurrent BCs are likely vulnerable to these genes-derived tumor suppressions." (PMID 37370814, 2023). "Three genes were established as tumor suppressors and eight were novel to BC, including HNRN, KPRP, CRCT1, and FLG2." (PMID 37370814, 2023). "Conversely, genes related to epithelial differentiation and keratinization (FLG, FLG2, HRNR, TCHH, KRT73), immune regulation and tumor suppression (HLA-G, UNC5D), and metabolic signaling were downregulated, reflecting loss of tissue integrity and immune control." (PMID 41900972, 2026). "In addition to possessing tumor-suppression functions, these taxifolin-induced genes (HRNR, FLG2, CRCT1, and KPRP) reside in 1q21.3 and are coamplified in recurrent BCs with 1q21.3 amplification." (PMID 37370814, 2023). "Compared with patients with tumor size no more than 5 cm, the mutation percentages of ALB, FBN3, HSPG2, and FLG2 were increased in patients with tumor size more than 5 cm." (PMID 32017470, 2020).